KRAS (KRas proto-oncogene, GTPase)
Diseases named in the same sentence as KRAS in open-access papers (continued):
Sharing a sentence is not in itself a finding about the gene and the disease.
cancer (continued). "Another level of complexity is involved in this research, as the implications of our results extend beyond KRAS and NSCLC, suggesting the platelet-mediated oncogene transfer could be a broader phenomenon, potentially relevant to other oncogenes and cancer types." (PMID 40244100, 2025). "Given the critical role KRAS plays in immune suppression within the TME, G4 ligands targeting KRAS may offer a novel avenue for enhancing the efficacy of immunotherapies in KRAS-driven cancers." (PMID 40333779, 2025). "While miRNAs have been explored for their potential in targeting KRAS gene mutations, they may not serve as optimal direct therapeutics for treating KRAS-mutant cancers." (PMID 39820726, 2025). "Furthermore, their cytotoxic effect was independent of the KRAS pathway and the RAS mutational status of the cancer cells." (PMID 40076255, 2025). "However, they do not effectively target other KRAS mutants, such as KRAS G12D, KRAS G12S and KRAS G13, which are more common in other types of cancer." (PMID 39820726, 2025). "Moreover, the introduction of promiscuous G4 stabilizing molecules, such as CX-5461, in combination with PPRHs could further enhance KRAS and MYC silencing in dependent cancers." (PMID 39457457, 2024). "One is that the pro-oncogenic role we have uncovered for KRAS in nuclear protein export provides at least a partial explanation for the limited clinical success when inhibitors of canonical RAS signaling, such as MEKi and PI3Ki, have been used in cancer treatment." (PMID 39528835, 2024). "Studies have shown that under nutrient-sufficient conditions, the proliferation of some KRAS-mutant cancer cell lines is not strongly affected, or is relatively little affected, by pharmacological inhibition of autophagy, RNAi-mediated acute ATG5/ATG7 knockdown, or CRISPR-mediated ATG7 knockdown." (PMID 39272847, 2024). "Cancer cells use non-mutational adaptations to resist a wide variety of single drugs or drug combinations, including inhibitors targeting BRAF, MEK, EGFR, and KRAS." (PMID 38668053, 2024). "Authors have hypothesised the potential use of KRAS mutation status as a predictive biomarker in the selection of patients for immune checkpoint inhibitors as no significant OS benefit was observed for patients with KRAS wild type cancers." (PMID 38439805, 2024). "Given the symbiotic relationship between KRAS, cancer stem cells, and fibroblasts, we hypothesized that CAF-derived factors might be responsible for driving cancer cell stemness in CRC cell lines, subsequently inducing resistance to KRAS-targeted inhibition." (PMID 39061234, 2024). "In cancer cells, combination of RAS(ON) G12C-selective and SHP2 inhibitors prevents MAPK reactivation, which extends the reversion of immune evasive mechanisms driven by oncogenic KRAS, such as secretion of immune evasive cytokines and inhibition of IFN responses." (PMID 39322643, 2024). "Certain cancer cells become independent of KRAS dependence by activating alternative pathways." (PMID 38655260, 2024). "However, ectopic expression of GLI-1 increased KRAS promoter activity in cancer cells without KRASG12C-inhibitor treatment, suggesting that GLI-1 plays a role in enhancing KRAS-promotor activity." (PMID 38225225, 2024). "KRAS-targeted inhibition (using inhibitors such as sotorasib or adagrasib) can also inadvertently activate Hippo signaling, which promotes the maintenance of EMT characteristics essential for cancer cells to overcome KRAS suppression and develop resistance against these inhibitors." (PMID 39061234, 2024). "It is known that hyperactivation of KRAS stimulates the downstream AKT and ERK pathways, which were reported to attenuate resistance to chemo-agents in carcinomas, therefore, whether BI-2865 reversed MDR through activating AKT and ERK pathways was further identified here." (PMID 38872211, 2024).
cancer (continued). "In addition to the KRAS and SALL4oncogenes, CGS4 tumors highly express cancer-testis antigens (CTAs) such as MAGEA3 and MAGEA12, indicating that they might be good candidates for testing CTA-mediated cancer vaccine therapy." (PMID 37674200, 2023). "However, it was later shown that incorporation of DHA and EPA into the plasma membrane phospholipids suppresses phosphatidic acid-dependent oncogenic KRAS-driven effector interactions (i.e., ERK signaling), thus suppressing hyperproliferation of cancer cells in vitro and in vivo." (PMID 36675307, 2023). "In both the 1L and 2L settings, a higher proportion of patients with KRAS G12C–positive tumors were female, were former or current smokers, and had tumors with a higher proportion of PD-L1–high and non-squamous histology than patients with KRAS WT cancer." (PMID 37069542, 2023). "Moreover, in vivo animal efficacy studies conducted in xenograft models of mutant KRAS demonstrated that SJ-C1044 treatment led to a dose-dependent reduction in cancer tissue growth, without the development of drug resistance." (PMID 37504287, 2023). "Using real-world data, we assessed the effect of KRAS G12C mutation with or without STK11 and/or KEAP1 mutations on overall survival (OS) in patients with aNSCLC receiving cancer immunotherapy (CIT), chemotherapy, or both in first line (1L) and second line (2L)." (PMID 37069542, 2023). "Historically, EGFR inhibitors have not been effective against KRAS-mutant cancers; however, second generation inhibitors have shown promise in treating both KRAS- and EGFR-mutant tumors by targeting all members of the ErbB family of proteins (EGFR/ERbB1, HER2/ErbB2, HER3/ErbB3, HER4/ErbB4)." (PMID 36674513, 2023). "Intriguingly, KRAS-driven cancers do not seem to follow this principle." (PMID 36675307, 2023). "Additionally, it is worth mentioning that aberrant activation of KRAS is responsible for dysregulation of the RAS/MAPK pathway, which is a pivotal and classical cascade response and contributes to the malignant biological behavior of cancer cells." (PMID 37716979, 2023). "Interestingly, while mSTK11-KEAP1 WT was also more prevalent in patients with KRAS G12C-positive cancer vs KRAS WT cancer (13.0% vs 9.0%; p = 0.05), STK11 WT-mKEAP1 was more prevalent in patients with KRAS WT cancer vs KRAS G12C-positive cancer (15.0% vs 7.0%; p < 0.001)." (PMID 37069542, 2023). "Genes positively correlated with purity showed enrichment in cancer-related pathways and processes such as epithelial-mesenchymal transition (BASP1, COL4A1, THBS2), genes involved in the TNFA signaling via NFKB (SPSB1, SMAD3), and genes upregulated by KRAS activation (CFB, MAFB)." (PMID 37041233, 2023). "Statins may activate the bone morphogenetic protein (BMP) pathway because these drugs are more effective in SMAD family member 4 (SMAD4)-expressing cancers but not KRAS mutant tumors." (PMID 38023258, 2023). "Because KRAS-altered tumors frequently harbor one of three classic hotspot mutations, nearly all studies have focused on these mutations, leaving significant functional ambiguity across the broader KRAS genomic landscape observed in cancer and non-cancer diseases." (PMID 37207265, 2023). "We found that doubling the sample size led to important cancer pathways being identified more stably and regularly in both the single-platform and cross-platform settings, including pathways related to ERB2, NFKB immune infiltration, and RAF in BRCA, and KRAS, MYC, and PRC2-related pathways in GBM." (PMID 36841852, 2023). "Additionally, other STK33 inhibitors, including ML-281, failed to rescue the survival rate of KRAS-dependent cancer cells." (PMID 38087254, 2023). "While previous groups have developed models to determine RAS activation and dependency in specific cancer types, there is no model that has identified a gene signature across all cancer types with predictive capabilities of KRAS dependency beyond the RAS pathway." (PMID 37141389, 2023).
cancer (continued). "Indeed, inhibiting KRAS’s enzymatic function of hydrolyzing GTP to GDP would prevent transitioning from its ‘on’ to ‘off’ state and would thus be counter-productive to interrupting the increased signaling seen in this pathway in a cancer setting." (PMID 37108538, 2023). "Serpin family I member 2 (SERPINI2), a tumor suppressor gene downregulated in PDAC and other cancers, and microRNA mir-217 (MIR217), a potential tumor suppressor gene in PDAC, which targets KRAS expression, were among the most underexpressed genes in the OCM tumors." (PMID 36579622, 2023). "Importantly, previous work has revealed that not all KRAS-mutant cell lines are KRAS-dependent, and that such KRAS-independent cancers exhibit features of an epithelial-mesenchymal transition (EMT) and apoptosis resistance." (PMID 37141389, 2023). "However, with ongoing progress in innovative technologies and increasing comprehension of the intricacies of KRAS signaling, there is growing optimism that targeting CRAF may constitute a pivotal component of cancer therapies." (PMID 38111008, 2023). "Currently, there is no effective therapy for the treatment of KRAS-mutant cancers." (PMID 37355626, 2023). "However, KRAS generally fails to convert precursor lesions into invasive cancers owing to triggering cellular senescence." (PMID 37591827, 2023). "Nevertheless, these mice do not develop cancer, and this effect is likely KRAS-independent." (PMID 36077614, 2022). "Although the impact of KRAS mutations on radiosensitivity and MET is not clear, it has been shown that KRAS can influence and rewire the metabolic state of cancer cells and, therefore, could contribute to the different sensitivities to MET." (PMID 36249066, 2022). "We anticipate that the use of RAS84 to stratify patients may validate observations that were made in preclinical models of KRAS-mutant cancers, but not confirmed in clinical studies." (PMID 36163168, 2022). "These include anti-EGFR monoclonal antibodies for KRAS wild type disease, combinations of anti-EGFR monoclonal antibodies with BRAF inhibitors for BRAF mutant cancers, anti-HER2 therapies for HER2 altered cancers and immune checkpoint inhibitors for microsatellite instability (MSI) high cancers." (PMID 36295658, 2022). "Moreover, BRAF mutated cancers with and without PIK3CA mutations are characterized by the absence of KRAS mutations and a lower prevalence of APC mutations than BRAF wild type counterparts." (PMID 36079062, 2022). "However, as reported in the Cancer Cell Line Encyclopedia, of the three OCCC cell lines employed in the current study, ES2 and JHOC5 have no activating mutations in the KRAS signaling pathway." (PMID 34965029, 2022). "Of note, although UCP2 is overexpressed in many cancer types, its expression is not induced by KRAS mutations, since the expression of the G12V mutant in BxPC3, a PDAC cell line carrying the wild-type form of KRAS, did not alter the expression of UCP2." (PMID 35008407, 2022). "Unlike for KRAS, oncogenic mutations in RRAS2 are rarely found in human cancer." (PMID 35120522, 2022).
cancer (continued). "In summary, ample experimental evidence indicates that activation of the MAPK pathway is essential for KRAS‐driven LUAD, but at the same time it might be equally relevant for normal homeostasis, thus posing a substantial barrier to the treatment of cancer patients." (PMID 34951114, 2022). "While exhibiting both mutations in a single cell may be selected against, it does not mean that an EGFR mutant cancer cell would be at a disadvantage in a community of KRAS-mutant cancer cells and vice-versa." (PMID 35061724, 2022). "Collectively, our findings suggest that combinatorial targeting of DDR1/BCR-ABL with EGFR-ERBB2 signaling may offer a therapeutic strategy against stem-like KRAS-driven chemoradioresistant tumors of COAD and GBM, widening the window for its applications in mainstream cancer therapeutics." (PMID 35664781, 2022). "Interestingly, KRAS depletion leads to a decrease in survivin levels in cancer cells harboring KRAS mutants, but not wild-type KRAS." (PMID 35883626, 2022). "However, some recurrent cancer drivers (KRAS, PI3KCA, NRAS, NF1) were reported to drive non-cancer clonal expansion only in one or two organ systems." (PMID 35078504, 2022). "The reasons for this divergence involving KRAS and BRAF mutations in cancer cells lacking Furin are not presently clear, but several mechanisms may be postulated." (PMID 35267511, 2022). "In the context of cancer treatment, it was found that a combination of BCL-xL inhibitors together with MEK inhibitors could be efficient against KRAS mutant cancer models, highlighting cross-talk between the MAPK and the mitochondrion-dependent apoptosis pathways." (PMID 35456874, 2022). "Importantly, sonic hedgehog-activated stellate cells secreted factors, were able to induce total proteome and phosphoproteome KRAS-non-autonomous changes, impacting cancer cell functional phenotypes." (PMID 35805073, 2022). "Therefore, SHP2 inhibition may diminish the upstream signaling from RTK and impair KRAS protein activation, leading to a broad enhancement of the effect of KRASG12C inhibitors on KRASG12C-mutant cancer cells." (PMID 35053550, 2022). "Notably, an increasing number of research studies have indicated that SHP2 inhibitors show efficacy in subsets of RTK-, KRAS-, and BRAF-driven cancers, although it has been previously reported that cancer cells carrying oncogenic RAS/RAF mutations would be refractory to SHP2 inhibition." (PMID 35462913, 2022). "First, the stratification by KRAS and BRAF mutations may not be present in this specific subpopulation, as the patients involved in this study received surgery of the primary cancer without removing the metastasis." (PMID 35587572, 2022). "In these cancers, KRAS is responsible for approximately 45% of cases in CRC, 35% in NSCLC and 90% in PDAC with poor prognosis and resistance to standard-of-care chemotherapy, denoting a critically unmet medical need that requires novel therapies to target KRAS2." (PMID 36273239, 2022). "Regardless of the cellular origin, the predominant cancer phenotype seems to be the endometrioid-like malignancy found in the ovary, suggesting that the activating KRAS mutant protein may dominantly dictate the malignant phenotype." (PMID 35159108, 2022). "We investigated signaling pathways in PC cells involved in the anti-cancer effects of laminarin by quantifying mitogen-activated protein kinase (MAPK) and Ak strain transforming (AKT) phosphorylation and Kirsten rat sarcoma viral oncogene homolog (KRAS) activity." (PMID 36139787, 2022).
cancer (continued). "Thus, PTPN2 knockdown significantly reduced proliferation and promoted apoptosis in KRAS-dependent cancer cells (HCT-116, PaTu8988T, and H460), but not in KRAS-independent cells." (PMID 36077422, 2022). "Within the KRAS G12R mutated group, patients with co-occurring PI3K mutations had numerically shorter OS compared to patients with cancers without PI3K mutations (19.4 vs. 24.2 months, P = .17), but had similar PFS (12.2 vs. 12.6 months, P = .83) with first-line systemic therapies." (PMID 36124727, 2022). "We next explored KRAS expression in different cancers compared to normal tissue, and discovered that it is highly expressed in eight cancers (BRCA, CHOL, ESCA, HNSC, LIHC, LUAD, LUSC, and STAD) while it has low expression in four cancers (COAD, KIRC, READ and THCA)." (PMID 35563733, 2022). "In addition, bile could be used to detect genomic alterations in BTC that are cancer-targeted therapy-related candidates, such as the ERBB2, FGFR1, FGFR2, FGFR3, KRAS, and WNT pathways." (PMID 36091112, 2022). "The results reveal that the expression levels of KRAS are significantly correlated with the infiltration levels of B cells, CD8+T cells, CD4+T cells, macrophages, neutrophils, and dendritic cells in 10, 13, 8, 9, 11, and 7 cancer types, respectively (correlation threshold ∣ R > 0.2, p < 0.05)." (PMID 35563733, 2022). "Interestingly, Nichols and colleagues demonstrated that in several MAPK pathway mutant cancer-driven cancers, including non-V600E, class 3 BRAF mutant-driven cancers, NF1 deletion-driven cancers, and KRAS G12C mutant cancers, SHP2 inhibition is effective at inhibiting downstream MEK/ERK signaling." (PMID 35905710, 2022). "RADIL and IPO7 depletion, relative to the luciferase control knockdown, significantly reduced cell viability of cell lines harboring the mutant or WT KRAS, suggesting that these genes are important, but disrupting them does not produce specific toxicity in KRAS mutant cancer cells." (PMID 35839996, 2022). "In the present study, our results showed that KRAS mutants in ctDNA did not predict cancer relapse." (PMID 35312176, 2022). "As a whole, our results point to KRAS being the crucial signaling effector that is responsible for facilitating MET-driven growth in METΔexon14-addicted cells, while also playing a role in maintaining growth and tumourigenesis in MET WT-addicted cancer cells as well." (PMID 35326531, 2022). "Taken together, our work shows that targeting DDR1, BCR-ABL, or DDR1/BCR-ABL with EGFR-ERBB2 could offer a potential therapeutic strategy against WNT-activated (stem-like) and KRAS-mutant COAD, with translatable applications in stem-like refractory cancers such as GBMs." (PMID 35664781, 2022). "Furthermore, we found that mutations of KRAS and ARID1B were also mutually exclusive in right-site cancer, but not in other sites." (PMID 36439454, 2022). "Our data demonstrate that initiating genetic events (EGFR-mut, KRAS-mut or variable in NEK) influence the subsequent pattern of stabilizing and directional selection on other genes and molecular pathways consistent with driver-dependent coadapted syndromes for each cancer type." (PMID 36612014, 2022). "KRAS mutations were detected in 45/73 non-PPE samples (61.64%); the frequencies of which were significantly different among normal (43.18%), hyperplasia (87.50%), EAH (90.91%), and carcinoma lesions (55.56%, P < 0.01)." (PMID 35796805, 2022). "This disrupted the cell proliferation in cancer cells, but not in cells with wild-type KRAS." (PMID 34781949, 2021).